UCP1 (uncoupling protein 1)
Diseases named in the same sentence as UCP1 in open-access papers (continued):
Sharing a sentence is not in itself a finding about the gene and the disease.
Obesity (continued). "This is in contrast to the Ucp1‐KO mice, where Ucp1 deletion causes obesity exclusively at thermoneutrality, without changes in body weight at 22°C." (PMID 28539390, 2017). "In addition, recent research revealed that group 2 innate lymphoid cells were necessary to the IL-33-induced beiging of white adipose tissue and the limiting of obesity through IL-4 receptor signaling, accompanied with the up-regulation of Ucp1 expression." (PMID 28806763, 2017). "Moreover, its ablation allows WAT UCP1 expression and browning mediated by normal levels of T3 with the consequent increase in EE ameliorating obesity and diabetes." (PMID 29021624, 2017). "We suggest the manipulation of the SIRT1 activity and its potentially-coupled regulation of UCP1 could be a possible future drug target in anti-obesity treatment." (PMID 28481291, 2017). "In fact, earlier studies showed that enhanced expression of UCP1 in WAT of mice can reduce obesity." (PMID 27616737, 2016). "Furthermore, adipocyte HIF2α is integral to the thermogenic response of BAT in obesity by regulating UCP1 expression." (PMID 26572826, 2016). "Brown adipose tissue (BAT) dissipates energy through Ucp1-mediated uncoupled respiration and its activation may represent a therapeutic strategy to combat obesity." (PMID 27461402, 2016). "In addition to its action in the adipose tissue, UCP1 contributes to the ability of the organism to oxidize substrates, metabolize lipids, and reduce weight, so high UCP1 expression should prevent the development of obesity." (PMID 26959981, 2016). "Therefore, this was another reason for interest in fat tissue markers (especially UCP1 and omentin) expression comparison in EC patients with “standard” and “metabolically healthy” obesity." (PMID 27853670, 2016). "Therefore, UCP1 expression in WAT has been regarded as a main reason for the anti-obesity and anti-diabetic effect of Fx." (PMID 26248075, 2015). "Besides, HFD also activated the compensatory energy-consuming process for anti-obesity through the up-regulation of UCP1 in BAT." (PMID 25747866, 2015). "UCP1 expression in WAT is an attractive target for the development of anti-obesity therapies." (PMID 26248075, 2015). "Moreover, muscle-specific ectopic expression of UCP1 leads to increased energy expenditure, delayed diet-induced obesity development, improved glucose homeostasis, increased insulin stimulated glucose uptake, and increased lipid metabolism." (PMID 25713540, 2015). "Therefore, it is possible that novel therapeutic agents activating or elevating the expression of PGC-1α and UCP1 would have crucial impacts on increasing the energy expenditure to ultimately prevent obesity." (PMID 24624222, 2014). "This study provides evidence that combining β3-adrenergic stimulation with PPARα activation can promote metabolic effects that stimulate energy expenditure, including UCP1-mediated thermogenesis, providing a potential therapeutic approach for the treatment of obesity." (PMID 24159189, 2014). "Considering the energy-dissipating ability of UCP1 by β3-adrenergic stimulation, the enhancement of its expression and activation by transcription factors and coactivators can be a promising strategy for anti-obesity and anti-diabetic drug therapy." (PMID 24159189, 2014). "In a thermoneutral environment, Ucp1-ablated mice gain weight compared to wild-type mice, whether on normal or high-fat diets, suggesting that the Ucp1 protein has an influence on the development of obesity." (PMID 25393240, 2014). "The observation that UCP1-mediated thermogenesis through β3-adrenergic activation is required for maximal stimulation of energy expenditure have important implications for the treatment of human obesity." (PMID 24159189, 2014). "AR KO mice show late onset of obesity despite ameliorated lipolysis and UCP1 expression." (PMID 24608114, 2014). "Lastly, 2-PCPA was also effective in reducing obesity in genetic UCP1 null mice." (PMID 24586592, 2014).
Obesity (continued). "At this temperature loss of UCP-1 seemed to have no impact on mouse susceptibility to a high fat diet induced obesity." (PMID 23504620, 2013). "In conclusion, UCP1 -3826A/G was significantly associated with VFA in a season-dependent manner, supporting the importance of cold stress in the activation of BAT and the significance of BAT in the development of obesity in adult humans." (PMID 24086366, 2013). "Thus, UCP1 knock-out mice are cold sensitive and tend to develop obesity, even when fed a control diet, whereas experimental approaches aiming to increase the amount and activity of brown AT reduce the development of obesity." (PMID 24040023, 2013). "While recent research has indeed confirmed the presence of brown adipocytes in humans, the relationship between these UCP1 positive adipocytes and energy expenditure, particularly in relation to clinical outcomes such as obesity and insulin sensitivity, remains to be seen." (PMID 23691283, 2013). "However, a moderate induction of UCP1 expression in white fat (10% of brown fat levels) or skeletal muscle (1% of brown fat levels) can be sufficient to protect against obesity, even despite a 35% decline in brown fat mass." (PMID 23460811, 2013). "Therefore, visceral fat area, rather than BMI, was thought to be the superior phenotype for testing the associations of UCP1/ADRB3 and obesity." (PMID 24086366, 2013). "For example, while transgenic mice that over-express UCP1 from the adipocyte-specific aP2 promoter (aP2-UCP1 mice) are resistant to high fat diet-induced obesity because of the ectopic expression of UCP-1 in WAT, the excessive expression of UCP1 from the transgene also induced BAT atrophy." (PMID 24386355, 2013). "Adaptive thermogenesis by uncoupling protein-1 (UCP1) could be a physiological defense against obesity." (PMID 22611357, 2012). "The association of both FTO and UCP-1 polymorphisms with the obesity phenotype in the Brazilian population has not been reported, and that was the aim of the present study." (PMID 23134754, 2012). "Taken together we found evidence that rs9939609 in the FTO and rs6536991 in the UCP-1 gene increased the risk of obesity but not obesity related phenotypes in the Brazilian population studied." (PMID 23134754, 2012). "UCP-1 is a major obesity-related gene that regulates energy homeostasis inside body." (PMID 23043591, 2012). "It has been demonstrated that increased expression of UCP1 in brown adipocyte or ectopic expression of UCP1 in mouse or human skeletal muscle and white adipocyte promotes fatty acid oxidation and resistance to obesity." (PMID 23039759, 2012). "It is therefore important to note that there may be an opposite trend for the association between the UCP-1 gene A-3826G polymorphism and low HDL-cholesterolemia based on the obesity status of subjects." (PMID 22393344, 2011). "Based on this background information, the present study aimed to compare the association between the UCP-1 gene A-3826G polymorphism and low HDL-cholesterolemia in a general Japanese population by analyzing subject-groups separated according to their obesity status." (PMID 22393344, 2011). "On the other hand, ectopic expression of UCP1 in WAT results in resistance to obesity." (PMID 21193034, 2011). "Expression and activation of UCP1 in brown and white adipose tissue lead to dissipation of energy in the form of heat, and may thus protect against diet induced obesity." (PMID 21738749, 2011). "Our result may highlight again adrenoceptor-UCP1 system in pharmacological approach to obesity treatment, which has repeatedly been confirmed in experimental animals, but not yet approved in humans." (PMID 21701596, 2011). "On the other hand, other models of BAT dysfunction have a paradoxical resistance to obesity such as mice with targeted deletion of the UCP-1 gene, or deletion of all isoforms of TRα (Thra-0/0), or a knock in of a different dominant negative mutation in TRα (R384C)." (PMID 21698184, 2011).
Obesity (continued). "However, the recent demonstration that UCP1 ablation per se induced obesity when the mice were kept at thermoneutrality clearly indicates that UCP1 is important in diet-induced energy dissipation at thermoneutrality." (PMID 20613988, 2010). "β3-Adrenergic receptor (β3-AR) and uncoupling protein 1 (UCP1) are involved in energy expenditure of the adipocytes, and the polymorphism of these genes has been reported to be associated with the prevalence of obesity and type 2 diabetes." (PMID 20069060, 2009). "Adipose Tissue and Metabolic Effects: SGLT2is mitigate obesity-associated adiposopathy by shifting macrophage polarization (M1 to M2), reducing proinflammatory cytokines (TNF-α, IL-6), and enhancing adipose tissue browning (UCP1 upregulation) and mitochondrial biogenesis (via PGC-1α/PPARα)." (PMID 40863154, 2025). "Interestingly, in contrast to male Ucp1-deficient mice, female Ucp1-deficient mice were not resistant to diet-induced obesity when housed under mild cold conditions (18 °C)." (PMID 40702736, 2025). "Interestingly, it was recently shown that loss of HDAC11 in mice promotes thermogenic capacity by increasing UCP1 expression, stimulates brown adipose tissue formation, attenuates obesity and metabolic syndrome in response to high fat diet, and increases fatty acid oxidation metabolism." (PMID 40220154, 2025). "Clarification of factors affecting feline Ucp1 expression enables the control of mitochondrial respiration activity and thermogenesis in brown/beige adipocytes, which may lead to the prevention of obesity and obesity-related diseases in cats." (PMID 41193585, 2025). "Moreover, ZAG mRNA expression has been positively correlated with browning-related genes in subcutaneous white adipose tissue from patients with overweight and obesity, including uncoupling protein 1 and peroxisome proliferator-activated receptor gamma coactivator 1 alpha." (PMID 40564902, 2025). "This process, known as WAT browning, is characterized by the induction of uncoupling protein 1 (UCP1) and an increase in oxidative mitochondrial metabolism; the latter is beneficial for increasing energy expenditure and improving metabolic dysfunction in obesity-related disease models." (PMID 39465352, 2024). "Moreover, in vitro experiments, it was proved that EGCG could promote the mitochondrial biogenesis and UCP-1 expression of adipocytes by inhibiting Notch1 expression, so as to promote the browning of white adipocytes and improve obesity." (PMID 38893431, 2024). "Weight loss and browning effects of FGF21 persist in obesity as DIO male mice treated daily with FGF21 (1 mg/kg) for 2 weeks experience a 20% reduction in body weight without affecting food intake, and upregulated gene expression of Pgc-1α, and Ucp1 in WAT and BAT compared to controls." (PMID 39087083, 2024). "No major changes were seen in terms of adiponectin receptor 1 and UCP1 as a browning marker, a finding that is concurrent with others, particularly in clinical experiments where exercise fails to increase browning markers in adipose tissue in the context of obesity or activate brown adipose tissue." (PMID 38892984, 2024). "Additionally, elevated IL-27 levels may help prevent obesity by promoting uncoupling protein 1 (UCP1) production, enhancing adipocyte thermogenesis and energy expenditure in HFD-fed mice." (PMID 39765814, 2024). "High-fat diet induced obesity model mice studies illustrated that curcumin could inhibit the increased expression of uncoupling protein 1 (UCP1) in BAT, intervene the reduced of macrophage infiltration and altered macrophage functional polarity in WAT, of high-fat diet induced obesity mice." (PMID 37191432, 2023). "This is consistent with earlier studies that generally show that UCP1-ablated mice are more obesity-prone compared to wild-type mice when maintained at thermoneutrality and given high-fat diets, although this may not always be the case, as we have recently compilated." (PMID 37499977, 2023).
Obesity (continued). "The same molecule has also produced favourable results in rat models of type 2 diabetes (T2D) and obesity when administered by a nanochannel membrane device, providing a dramatic body weight reduction, normalization of cholesterol and glucose levels together with sustained expression of UCP1 in WAT." (PMID 37378828, 2023). "During the early childhood adiposity rebound—a critical phase that determines obesity risk later in life—the absence of adipose tissue UCP1 expression in children with normal body mass index (BMI) correlates with an obesity-associated gene expression signature." (PMID 38069028, 2023). "Firstly, it may be noted that the UCP1 gene itself has never appeared as a candidate gene in any genome-wide association study (GWAS) for obesity-related issues." (PMID 37661736, 2023). "As a clinically relevant outcome of this study, we also show that lack of adipose tissue UCP1 expression in children is an early indicator of adipose tissue expansion and could be used to identify obesity risk before the onset of clinical signs of obesity." (PMID 38069028, 2023). "Based on the summary here of the available data, it may be concluded that at least in mice, diet-induced thermogenesis may be observable under certain conditions and is as such located to brown adipose tissue, and its absence (as in UCP1 KO mice) may lead to obesity." (PMID 37661736, 2023). "Interestingly, browning, the conversion of white adipocytes (enlarged spherical cells storing lipids) to brown-like adipocytes (small cells dissipating heat), reduces insulin resistance and obesity, and induction of uncoupling protein-1 (UCP-1) is a distinct marker of browning." (PMID 36729332, 2023). "In this study, we hypothesised that the previously reported anti-obesity effects of CPEF in db/db mice are due to the induction of UCP1 and PPARα expression, and accordingly quantified UCP1 and PPARα expression, and protein oxidation levels in brown adipose tissue." (PMID 36835279, 2023). "Thus, although attempts to recruit UCP1 in humans may become successful as such, it is only if constant activation of the UCP1 is also achieved that amelioration of obesity development could be attained." (PMID 37499977, 2023). "Whole-body UCP1-deficient mice are sensitive to cold exposure but do not develop severe obesity." (PMID 36674862, 2023). "In a study involving human subjects, CQ treatment produced a decrease in obesity as evidenced by reductions in the circumference of waist and hip, increases in serum levels of leptin, and induction of white adipocyte browning with enhanced expression of uncoupling protein 1 (Ucp1)." (PMID 37629581, 2023). "In the present investigation, we have examined whether the acquisition of large amounts of UCP1 (in brown adipose tissue, as well as in brite/beige adipose tissue) in itself provides an augmented defense against diet-induced obesity and conveys an amelioration of other metabolic parameters." (PMID 37499977, 2023). "Thus, a true obesity-inducing effect of (unknown) alterations in UCP1 amount or its inherent or endogenously stimulated activity has not as yet been identified." (PMID 37661736, 2023). "Besides, Fx also possesses anti-obesity effects by regulating UCP1 levels and lipid metabolism, which may help to reduce BC risk." (PMID 35736173, 2022). "Thus, we hypothesized that melatonin suppresses the progression of obesity by increasing UCP1 expression dependent on FGF21." (PMID 36207302, 2022). "Given that brain FGF21 signaling promotes energy intake and is required for Ucp1 induction, it is possible that these characteristics of mice fed the high-fat KD0P are a result of FGF21 resistance, which has been associated with high-fat diet-induced obesity in mice." (PMID 35433789, 2022). "In addition, the anti-obesity effects of curcumin were abolished by the Ucp1 knockout." (PMID 35054828, 2022).
Obesity (continued). "Therefore, PRDM16, UCP1, CIDE-A, and COX1 gene expression can be a key strategy to reduce metabolic disorders caused by obesity because brown fat can increase energy consumption and protect against obesity through a specialized energy-burning program." (PMID 36093083, 2022). "Finally, in human transcriptome data we demonstrate for the first time that WAT MB expression is differentially regulated in obesity and correlates with UCP1 and other markers of adipose tissue (AT) browning, suggesting functional importance of MB expression in human AT." (PMID 36480426, 2022). "Thus, in obesity, batosomes are enriched with proteins involved in signal transduction, cell communication, the immune response, inflammation, thermogenesis, and potential obesity biomarkers including UCP1, Glut1, MIF, and ceruloplasmin." (PMID 36142750, 2022). "This study suggested the regulatory mechanism of UCP1 expression through cellular lipid metabolism, which may be indispensable to evaluate the browning effects during the screening of relevant molecules as anti-obesity drugs." (PMID 35805122, 2022). "Lastly, there are other UCP1 KO models that may be necessary to consider in order to objectively unravel the mechanistic targets of fish oil related to identifying targets to combat obesity and NAFLD." (PMID 34829779, 2021). "Thus, promoting the expression of UCP-1 and enhancing energy expenditure could be a promising approach to restrict obesity." (PMID 34222665, 2021). "Mainly Lactobacillus plantarum has proven successful in potentiating process of BAT thermogenesis via activating UCP1-dependent mechanisms when administrated in rats, and these results suggested that L.plantarum may thus inhibit the progression of obesity in animal models." (PMID 33923364, 2021). "Therefore, activation of UCP1 may be a promising therapeutic strategy to counteract obesity and NAFLD." (PMID 34829779, 2021). "Hence, UCP1-deficient mice also possess a positive metabolic phenotype indicating that beige fat biogenesis driven by adipose-specific overexpression of PRDM16 protects from cold-induced hypothermia, diet-induced obesity, and glucose intolerance." (PMID 34367068, 2021). "Moreover, our in vivo experiment results confirmed that SFN treatment substantially decreased the adipocyte size and body weight gain, and further prevented HFD-induced obesity through the browning of adipocytes via mitochondrial biogenesis and the activation of Ucp1 and Pgc1-α." (PMID 33995092, 2021). "Furthermore, in vivo FGF21 gene delivery protected C57BL6/J mice against diet-induced obesity by decreasing adiposity and increasing uncoupling protein 1–dependent thermogenesis in brown fat and by boosting respiratory capacity in subcutaneous and perigonadal white fat." (PMID 34074713, 2021). "Interestingly, in UCP1-deficient mice, GC-induced obesity was not worsened compared to wild-type mice, suggesting UCP1-independent effects of GCs on BAT function." (PMID 33927694, 2021). "Finally, compared with DBP + saline mice, TUDCA treated mice (DBP + TUDCA) showed decreased relative mRNA levels for Bip and Chop and higher UCP1 protein expression, suggesting that endoplasmic reticulum stress participates in DBP-induced obesity by suppression of UCP1." (PMID 33004990, 2020). "In addition, UCP1 has a role in regulation of cold and diet-induced thermogenesis, metabolic and energy balance and reducing the mitochondrial production of reactive oxygen species (ROS) that involved in the pathogenesis and progression of obesity and/or DM2." (PMID 32197395, 2020). "However, the overexpression of UCP1 does not reduce susceptibility to obesity when the mice are not challenged thermogenically." (PMID 32290353, 2020).